IL18 (interleukin 18)
Diseases named in the same sentence as IL18 in open-access papers (continued):
Sharing a sentence is not in itself a finding about the gene and the disease.
Arthritis (continued). "The role of IL-18 signaling has been examined in models of arthritis dependent on adaptive immune responses such as collagen-induced arthritis and antigen-induced arthritis." (PMID 37415987, 2023). "Targeting IL-18 via a neutralizing antibody, IL-18 binding protein (IL18BP) or using Il18−/− mice all significantly decreased the severity of arthritis and cartilage damage." (PMID 35567665, 2022). "IL-6, IL-17, and TNF-α is now generally accepted to play important roles in the pathogenesis of the arthritis subtype, whereas IL-1β, IL-18, and IFN-γ play central roles in the systemic subtype." (PMID 35778759, 2022). "In agreement, the severity of Collagen induced arthritis was reduced significantly in the course of treatment with polyclonal anti-IL-18 antibodies and was more effective compared to IL-18 BP." (PMID 36032110, 2022). "The same group subsequently made similar observations in patients with AOSD, where IL-18-dominant patients had higher ferritin levels but a lower frequency of arthritis as compared to IL-6-dominant patients." (PMID 34635157, 2021). "The present study showed that the serum levels of ferritin and IL-18 can be useful to objectively predict the treatment response of arthritis during the course of KD." (PMID 34354966, 2021). "In the multivariate analysis, arthralgia or arthritis, IL-18, and sIL-2R were extracted as independent predictive indicators." (PMID 34691064, 2021). "Univariate and multivariate logistic regression analyses revealed that IL-18, sIL-2R, and ‘arthralgia or arthritis’ are independent factors useful in the differential diagnosis of AOSD from adult HLH." (PMID 34691064, 2021). "IL-18 levels in the RA synovium are higher than in the osteoarthritis (OA) synovium, and IL-18 aggravates arthritis severity in a model of collagen-induced arthritis." (PMID 34530864, 2021). "The plasmid backbone and multiple immunoregulatory properties of IL-18 appear to play a major role in the pIL-18 coadministration with rIL-4-mediated immunomodulation of arthritis through blocking the TLR2/MyD88/NF-kappa B signaling pathway." (PMID 29854762, 2018). "Another study demonstrated that soluble IL-18 receptor β inhibited IL-18 during experimental arthritis, had a major effect on T-cell cytokine balances, and led to aggravation of CIA." (PMID 29854762, 2018). "Surprisingly, IL-18 gene therapy combined with IL-4 significantly reduced the mean arthritis score of our murine model." (PMID 29854762, 2018). "Our previous research suggested that recombinant murine IL-18 (rmIL-18) treatment alone ameliorated the progression of arthritis in mice with CIA and that coadministration with low-dose rIL-10 reversed this effect." (PMID 29854762, 2018). "The plasmid backbone and multiple immunoregulatory properties of IL-18 appeared to play the major role in the pIL-18 coadministration with rIL-4-mediated immunomodulation of arthritis through blocking the TLR2/MyD88/NF-kappa B signaling pathway." (PMID 29854762, 2018). "Our previous report showed that combined treatment of low-dose IL-18 with IL-10 can prevent the progression of arthritis in CIA mice and that this is mediated by a GATA-3-dependent mechanism." (PMID 29854762, 2018). "IL-18 is broadly expressed in osteoblasts from subchondral bone, which play a critical role in bone remodeling during arthritis." (PMID 28448439, 2017). "IL-18 functions as an angiogenic mediator during arthritis, and YKL-40 is a secretory product in arthritic disease; its role in IL-18 production and angiogenesis has been uncertain until now." (PMID 28448439, 2017). "The elevated IL-18 in RA synovium contributes to arthritis, resulting in severe inflammation, including inflammatory cell infiltration and pannus formation." (PMID 27823968, 2016). "Several of these genes, including phospholipase A2, kallikrein, IL-18, and CX3CL1, have been associated with arthritis or inflammatory pain." (PMID 21689431, 2011).
Arthritis (continued). "The better to define the activity of IL-18 to induce inflammatory responses in acute models of arthritis, we administered to both Wt and IL-18 gene-knockout mice a single intraarticular (i.a.)injection of zymosan, inducing ZIA over a 48-hour period." (PMID 20565717, 2010). "In streptococcal cell wall (SCW)-induced arthritis, neutralizing rabbit anti-murine IL-18 antibody suppressed joint swelling." (PMID 20565717, 2010). "We clarified the cytokines induced by IL-18 in zymosan-induced arthritis (ZIA) by comparing cytokine levels from ZIA arthritic joints homogenized from IL-18 gene-knockout and Wt mice." (PMID 20565717, 2010). "In another study, IL-18 knockout mice showed a reduced degree of inflammation, and the administration of recombinant IL-18 reversed collagen-induced arthritis." (PMID 16563174, 2006). "One reason why haplotype S01 of the IL18 gene is skewed in Japanese arthritis patients is due to a basal high frequency of the haplotype S01 in the Japanese population." (PMID 16563174, 2006). "As described, IL-18 would be involved in the pathogenesis of arthritis directly or via production of other cytokines, and probably would promote a Th1-type immune response." (PMID 16563174, 2006). "Importantly, IFN-γ priming of monocytes from PAPA (pyogenic arthritis, pyoderma gangrenosum and acne) syndrome patients induces a pyrin-dependent IL-18 release and JAK inhibitors have a beneficial effects on the skin lesions of these patients." (PMID 39868044, 2025). "The intestinal microbiota could trigger systemic immune responses and arthritis via the IL-18/IL-18R pathway and metabolic products." (PMID 38711505, 2024). "Similarly, IL-18R alpha-deficient mice exhibited an attenuated form of arthritis with reduced synovial CD4 T cell and macrophage infiltration as well as lower serum levels of IL-6, IL-18, TNF-α and IFN-γ as compared to WT mice." (PMID 37415987, 2023). "Dysregulation of IL-18 levels may lead to autoimmune or inflammatory diseases involving host defence, cancer, allergy, immune response, arthritis, etcetera." (PMID 38031150, 2023). "Indeed, in this model, IL-18 KO mice developed similar arthritis scores and antigen-stimulated T-cell proliferation and IFN-γ production to WT mice." (PMID 37415987, 2023). "Indeed, the administration of either a neutralizing anti-IL-18 antibody or rhIL-18BP significantly attenuated the severity of arthritis and cartilage degradation as compared to placebo-treated mice." (PMID 37415987, 2023). "The role of IL-18 was examined in two models of arthritis depending on innate immune responses." (PMID 37415987, 2023). "In Streptococcal cell wall-induced arthritis, the use of neutralizing rabbit anti-IL-18 antibodies significantly attenuated the severity of joint swelling and the local production of pro-inflammatory cytokines and prevented the inhibition of cartilage proteoglycan synthesis." (PMID 37415987, 2023). "In fact, serum IL-18 correlates with disease activity, thus suggesting that a functional relation may exist between IL-18 and arthritis." (PMID 37415987, 2023). "Moreover, IL-18 was found to be redundant in antigen-induced arthritis in response to an intra-articular injection of bovine serum albumin in mice immunized against this antigen." (PMID 37415987, 2023). "Indeed, arthritis severity was markedly attenuated in IL-18 knock-out (KO) mice, as well as by the administration of neutralizing anti-IL-18 antibodies and recombinant human IL-18BP." (PMID 37415987, 2023). "In some patients, MAS may compete with IFNg-independent features like arthritis, and IL-18 may contribute to both." (PMID 36096831, 2022). "The serum levels of ferritin and IL-18 or the combination of clinical covariates at the onset of arthritis may help us to predict the treatment response and prognosis of arthritis." (PMID 34354966, 2021).
Arthritis (continued). "The serum levels of ferritin and IL-18 at the onset of arthritis may be a good predictive biomarker to distinguish among these three types of KD-related arthritis." (PMID 34354966, 2021). "Data from the literature suggest that different cytokine profiles may be responsible for distinct clinical manifestations, as systemic subsets seem to present with high levels of IL-18 and IL-1β while patients with arthritis exhibit higher IL-6 serum levels." (PMID 34203779, 2021). "To determine whether CIA-induced arthritis stimulates the IL-18/IL-18Rα signaling pathway, we measured the mRNA expressions of IL-18 and IL-18Rα in the synovium of WT DBA/1J after an LPS injection by real-time PCR." (PMID 31861496, 2019). "The allele IL18-607C has been linked to hepatitis C susceptibility and chronic obstructive pulmonary disease, and the genotype C/C has been associated with higher IL-18 production in multiple sclerosis; IL18-137G was associated with the risk of arthritis and IL18-137G/C genotype with oral cancer." (PMID 31065235, 2019). "In a collagen-induced experimental arthritis model, JQ1 induced attenuation in the arthritis severity score associated to lower serum levels of proinflammatory cytokines, including IL-1β, IL-6, IL-17, and IL-18." (PMID 31780938, 2019). "Our results demonstrated that the severity of arthritis was improved by suppressing serum inflammatory cytokines and the synovium cytokine mRNA expressions (especially those of IL-18, IFN-γ, TNF, and IL-6) and by suppressing the accumulation of CD4+ T cells in IL-18Rα KO mice." (PMID 31861496, 2019). "Sweet cherry consumption could therefore help to reduce the risk of arthritis (indicated by CRP, TNFα, IL-18 and IL-1Ra), cardiovascular disease (CRP, ferritin, ET-1, EN-RAGE, PAI-1 and IL-18), cancer (ET-1), and hypertension (ET-1)." (PMID 28732012, 2017). "In addition, IL-32 expression was correlated with IL-18 expression in the synovia of experimental arthritis animals and mucosa of patients with allergic rhinitis." (PMID 26634249, 2015). "IL-18 is thought to play a major role in the chronicity of inflammation in this arthritis model." (PMID 22414623, 2012). "Another possible mechanism by which statins may affect arthritis is through their induction of caspase-1, IL-1β, and IL-18 in monocytes, resulting in increased IFNγ production by T cells." (PMID 22537858, 2012). "Finally a local overexpression of several cytokines/adipocytokines poorly described in arthritis (IL-13, IL-18, leptin) was observed." (PMID 22414623, 2012). "Taking the two possible mechanisms together, caspase-1 activation by statins may aggravate arthritis by inducing IL-1β and IL-18." (PMID 22537858, 2012). "Our data show that IL-18 recruits monocytes in vivo, may be produced early in the acute phase of arthritis, and signals via p38 and ERK1⁄2 to recruit PB monocytes to STs." (PMID 20565717, 2010). "In collagen-induced arthritis, IL-18 promotes arthritis via tumor necrosis factor-alpha induction." (PMID 16563174, 2006). "Among three haplotypes of the IL18 gene, haplotype S01 might contribute genetically to the development of arthritis in the Japanese population." (PMID 16563174, 2006). "In ERA, distinct inflammatory responses associated with enthesitis or arthritis may be localized and not fully captured in blood gene signatures, with the exception of the IL-18 signaling pathway." (PMID 39923112, 2025). "In addition, IL-18 may link systemic inflammation with pathological bone remodelling in arthritis due to induction of osteoclast formation and accelerated bone resorption." (PMID 35160217, 2022). "Higher expression levels of IL-18 mRNA were observed in synovial biopsies from patients with active AOSD compared to healthy controls, suggesting that IL-18 may be associated with joint pain or arthritis in individuals with AOSD." (PMID 34691064, 2021).
Arthritis (continued). "Finally, the ability of IL-18 to induce a cytokine cascade during acute joint inflammatory responses was examined by inducing wild-type (Wt) and IL-18 gene-knockout mice with zymosan-induced arthritis (ZIA)." (PMID 20565717, 2010). "The effect of IL-18 was apparently independent of IFN-γ, because anti-IL-18 antibodies could equally inhibit SCW arthritis in mice deficient in IFN-γ." (PMID 20565717, 2010). "Interactions between IL-18 and STAT3 have been shown in a spontaneous arthritis model, where the activation of STAT3 mediated IL-23-induced IL-17A production from CD4+ T cells." (PMID 40777291, 2025). "The systemic subtype shows higher IL-18 levels and is more frequently complicated by MAS than the arthritis subtype." (PMID 35778759, 2022). "In this study, we used the murine CIA model to examine the effect of gene transfer of an IL-18-expressing plasmid on suppression of CIA and the possible roles of Treg, Th2, Th1, Th17, and TLRs in the pathogenesis of arthritis." (PMID 29854762, 2018). "In contrast, other pro-inflammatory cytokines such as IL-6, IL-17, transforming growth factor-β, and IL-18 were clearly upregulated in AIA rats and considered to contribute to the pathogenesis of joint inflammation." (PMID 26546348, 2015). "Inflammation further exacerbates this degeneration, as inflammatory cytokines, such as interleukin‐1 beta (IL‐1β), IL‐6, IL‐18 and tumour necrosis factor‐alpha (TNF‐α), promote ECM degradation, highlighting inflammation as a critical driver of arthritis pathogenesis." (PMID 40179133, 2025). "The zymosan-induced arthritis model is characterized by the release of pro-inflammatory cytokines, such as tumor necrosis factor (TNF), interleukin-18 (IL-18), interleukin-1β (IL-1β), and interleukin-6 (IL-6); synovial joint hypertrophy; and leukocyte recruitment." (PMID 39194751, 2024). "In this larger dataset, levels of circulating IL-18 at diagnosis did not distinguish those with and without arthritis." (PMID 38183114, 2024). "Using IL-18BP and IL-18 KO mice, we showed that neither IL-18 nor IL-18BP was required to control the incidence and severity of arthritis." (PMID 37415987, 2023). "In accordance with the absence of difference in arthritis severity, Csf2 mRNA levels were comparable in IL-18 KO mice and WT littermates." (PMID 37415987, 2023). "Unfortunately, no data were available for MMP-3, ferritin, or the IL-18 level in one interval fever-onset patient with methotrexate-dependent arthritis (#25)." (PMID 34354966, 2021). "Among the five variables, including age, serum levels of ferritin, IL-18, and MMP-3 level, and days of illness at the onset of arthritis, only ferritin showed a significant difference among interval fever-onset, continued fever-onset/non-biologic, and continued fever-onset/biologic patients." (PMID 34354966, 2021). "The number of patients with arthritis was significantly higher in the IL-6-dominant subgroup, while no patient in the IL-18-dominant subgroup presented with arthritis." (PMID 34203779, 2021). "It was reported that the expression of NLRP3, IL-18, and IL-1β in joint synovial fluid was significantly increased in mice with collagen-induced arthritis, and the expression of NLRP3 was correlated with the severity of clinical arthritis." (PMID 33430857, 2021). "Also, IL-18 is a cytokine that can be detected in active clinical SLE with anti-dsDNA, hypocomplementemia, and arthritis." (PMID 31842967, 2019). "In the present study, we demonstrated for the first time that IL-18-expressing plasmid gene combined with IL-4 skewed the balance of Th1/Th2/Th17 to a Th2 type and increased GATA-3 and Foxp3 expression on collagen-induced arthritis." (PMID 29854762, 2018). "In an expanded dataset on Dutch SJIA patients prospectively recruited with (n = 44) and without (n = 22) arthritis, patients without arthritis trended non-significantly higher in laboratory features associated with MAS, including sIL-2R, but with comparable IL-18 levels at onset." (PMID 38183114, 2024).
Arthritis (continued). "Zymosan caused systemic inflammation with a marked elevation in multiple pro- and anti-inflammatory cytokines TNF-α, IFN-γ, IL-13, G-CSF, M-CSF, IL-6, IL-18, IL-1α and IL-4 in arthritic rats (all arthritis groups pooled) versus the non-arthritic controls (0.001<p<0.05)." (PMID 33878143, 2021). "However, the occurrence of skin rash, arthritis, sore throat, lymphadenopathy, hepatosplenomegaly, leukocytosis, disease activity scores, and levels of ferritin, IL-1, IL-6, IL-17A, IL-18, TNF-α, LC3-II mRNA, or ATG16L mRNA expression was not predictive of the systemic pattern." (PMID 34208077, 2021). "Animals lacking IL-18 gene expression were less vulnerable to the arthritis induced by collagen (CIA), as compared with the control, suggesting the key role of the IL-18 cytokine in RA." (PMID 32545788, 2020).